MITF (melanocyte inducing transcription factor)
Diseases named in the same sentence as MITF in open-access papers (continued):
Sharing a sentence is not in itself a finding about the gene and the disease.
melanoma (continued). "It is not surprising that the ‘master regulator’ of melanocyte cell growth, maturation, apoptosis, and pigmentation – MITF – was the first gene determined as a target for miRNA-mediated regulation in melanoma." (PMID 19638982, 2009). "SK-MEL-28, a melanoma cell line considered to express relatively low levels of MITF, clustered with the lower MITF Motif 1 cell lines as expected." (PMID 20041153, 2009). "Critically, MITF re-expression rescued proliferation of melanoma cells when BRAF was depleted using RNAi, or when MEK was inhibited with PD184352." (PMID 18628967, 2008). "Through these opposing mechanisms, oncogenic BRAF executes exquisite control over MITF expression, ensuring that the protein levels are permissive for melanoma cell survival and proliferation." (PMID 18628967, 2008). "On tissue sections, identification of melanoma cells was achieved with an antibody against the microphthalmia transcription factor MITF, which produces a specific nuclear signal in melanocytes." (PMID 18442364, 2008). "Nonetheless, other cell lineage-specific transcription factors have been found amplified in cancers, including MITF in melanoma, AR in hormone-independent prostate cancer, ESR1 in breast cancer, and most recently NKX2-1 (TITF) in lung cancer." (PMID 18535672, 2008). "Critically, in melanoma cells MITF is required downstream of oncogenic BRAF because it regulates expression of key cell cycle regulatory proteins such as CDK2 and CDK4." (PMID 18628967, 2008). "Our data suggest that oncogenic BRAF plays a critical role in regulating MITF expression to ensure that its protein levels are compatible with proliferation and survival of melanoma cells." (PMID 18628967, 2008). "In summary, we show that oncogenic BRAF plays a critical role in regulating MITF expression in melanoma cells, using apparently opposing mechanisms to exquisitely regulate the levels of this critical transcription factor." (PMID 18628967, 2008). "We have previously shown that the differentiation functions of MITF occur at high protein concentrations, and accordingly, high levels of MITF are anti-proliferative in melanoma cells." (PMID 18628967, 2008). "The lineage-specific oncogene, MITF, previously shown to act as a master regulator of melanocyte development and a critical survival oncogene amplified in melanoma, showed a 3.7 fold increase." (PMID 18442402, 2008). "We posit that because constitutively active ERK is so efficient at down-regulating MITF in BRAF mutant melanoma cells, it is necessary for the cells to rescue MITF expression to ensure that they can continue to proliferate and survive." (PMID 18628967, 2008). "Consistent with this, we show that BRN2 and MITF expression occur coincident with oncogenic BRAF in human melanoma samples." (PMID 18628967, 2008). "Despite all the evidence suggesting that MITF must be down-regulated for melanoma progression, MITF expression is essential for proliferation and survival of melanoma cells because it regulates genes such as CDK2 and BCL-2 respectively." (PMID 18628967, 2008). "Formalin fixed tissue from 4 normal skin biopsies, 14 nevi, 5 cutaneous and 18 metastases of melanoma were analysed using MITF as melanocytic marker." (PMID 18442364, 2008). "In summary, we have shown that BRN2 induces MITF mRNA expression in human melanoma cells and that through BRN2, V600EBRAF can stimulate transcription of the MITF gene in both melanoma cells and melanocytes." (PMID 18628967, 2008). "Although MITF is able to induce cell cycle arrest in melanocytes and melanoma cells in a p16 and p21 dependent manner, MITF gene was found to be amplified in melanoma and its overexpression induced transformation and drug resistance in BRAF mutant melanocytes." (PMID 18211678, 2008).
melanoma (continued). "Previous studies have shown that V600EBRAF stimulates melanoma cell proliferation and here we show that MITF is required for proliferation in these cells, because MITF depletion blocks DNA synthesis in BRAF mutant melanoma cells." (PMID 18628967, 2008). "RACK1 overexpression was consistently observed in all MITF+ cells from each of the 23 malignant melanoma samples examined." (PMID 18442364, 2008). "We have previously shown that because ERK is hyper-activated in melanoma cells in which BRAF is mutated, the MITF protein is constitutively down-regulated." (PMID 18628967, 2008). "The data above place BRN2 between V600EBRAF and MITF in melanoma cells and this is consistent with our previous study showing that BRN2 is downstream of V600EBRAF." (PMID 18628967, 2008). "MITF is essential for the survival of pigmented cells, but whereas high levels of MITF drive melanocyte differentiation, lower levels are required to permit proliferation and survival of melanoma cells." (PMID 18628967, 2008). "We have gone on to show that as a consequence of ERK being constitutively activated in melanoma cell lines expressing oncogenic BRAF, MITF protein levels are lower in mutant BRAF melanoma cells than in melanocytes." (PMID 18628967, 2008). "The strong activation of MITF/Bcl‐2 pathway is one of reasons that lead to acquired resistance of MEK inhibitor for NRAS‐mutant melanoma, and anti‐Bcl‐2 (ABT‐199) annihilated the acquired resistance and restored the sensitivity of NRAS‐mutant melanoma cells to MEK inhibitor." (PMID 41492362, 2026). "In addition, low SCD activity leads to ER stress and inflammatory signaling (Via ATF4 and NF-κB), further suppressing MITF and enhancing melanoma cell plasticity and metastasis." (PMID 41596686, 2026). "Meanwhile, the dysregulation of MITF appears of critical importance for melanoma drug resistance." (PMID 41492362, 2026). "Interestingly, the reduced MiTF expression observed in larger and more mitotically active tumors, such as oral/digit melanomas, appears to contrast with its known role in promoting carcinogenesis." (PMID 41604042, 2026). "This study aimed to evaluate the expression of MiTF and p38 in canine melanomas using immunohistochemical assays and to verify the correlations between this expression and the presence of an inflammatory infiltrate, tumor size, mitotic index, and animal survival." (PMID 41604042, 2026). "Fatty acid metabolism regulates melanoma progression by influencing MITF expression." (PMID 41596686, 2026). "In addition to its pro-survival role in melanoma, recent studies have shown that MITF expression has important implications for cancer progression and treatment in other cancer types." (PMID 42268265, 2026). "Notably, almost all melanomas with TILs classified as BRISK B exhibit MITF expression levels above 50%." (PMID 39976551, 2025). "MITF protein expression is crucial for melanoma cell survival and proliferation." (PMID 39976551, 2025). "This suggests that canonical Wnt signaling may directly contribute to metabolic mitochondrial reprogramming via regulation of MITF-mediated effects on mitochondrial biogenesis in BRAF mutant melanomas." (PMID 40558548, 2025). "Additionally, MITF expression was significantly higher in cases where melanoma had spread to the sentinel lymph node (H ═ 5.21, P ═ 0.022)." (PMID 39976551, 2025). "We analyzed MITF protein expression across various clinical and pathological subgroups of melanoma." (PMID 39976551, 2025). "The subcellular distribution of MITF can therefore markedly influence melanoma cell behaviour." (PMID 41465475, 2025). "Therefore, to elucidate the unidentified effects of the antidiabetic regents, FABP5, ANGPTL4 and/or MITF on diabetic states of MM, high-glucose-induced metabolic and redox alterations were studied using melanoma A375 cells." (PMID 39940783, 2025).
melanoma (continued). "However, in melanomas with spindle cell morphology, MiTF is less reliable, as it can be expressed in non‐melanocytic spindle cell tumors, including dermatofibromas, schwannomas, leiomyomas, and leiomyosarcomas." (PMID 40509563, 2025). "Additionally, miTF acts a master regulator in melanoma and Ki-67 plays a proliferation marker, reflecting tumor aggressiveness and predicting prognosis." (PMID 40708947, 2025). "In addition, VIP increases ACTH levels in neonate rats and induces melanin synthesis via up‐regulation of CREB, MITF and Tyr in murine melanoma cell lines (B16F10;)." (PMID 39910963, 2025). "This indicates a dual role of YAP in the control of MITF in melanoma." (PMID 40973828, 2025). "They demonstrated that 7,8-DHF inhibited the growth of B16F10 melanoma cells without inducing cytotoxicity by downregulating microphthalmia-associated transcription factor (MITF) and its downstream targets." (PMID 41463545, 2025). "Interestingly, MiTF regulates melanocyte development and functions as both a melanoma oncogene and tumor suppressor, depending on its expression level." (PMID 40509563, 2025). "Dysregulation of MITF promotes oncogenic functions in melanoma." (PMID 40343114, 2025). "MITF regulates genes important for proliferation, differentiation, senescence, invasion, metastasis and metabolism and several lncRNAs act within the MITF network in melanoma." (PMID 41336739, 2025). "Protein expression levels of known melanoma markers, such as MITF, MLANA, PMEL, TYR, and SOX10, had the lowest expression in EC-Mit samples (ANOVA, FDR < 6 × 10−4) and had a significantly lower expression in the EC-like subtypes when compared to the Mit-like subtypes." (PMID 40075679, 2025). "The ACLY lipid synthesis enzyme activates the P300 acetyltransferase, leading to histone acetylation at the microphthalmia-associated transcription factor (MITF) locus and increased transcription of the MITF-PGC1α axis, promoting melanoma progression and resistance to MAPK inhibitors." (PMID 40539068, 2025). "This study examined the relationship between microphthalmia-associated transcription factor (MITF) expression and the immune microenvironment in primary melanoma using a modified classification of tumor-infiltrating lymphocytes (TILs) based on conventional BRISK categories." (PMID 39976551, 2025). "Conversely, downregulating MITF can also contribute to the modulation of the melanoma cell phenotype with an affected immune response, although immune evasion by MITFhigh melanoma cells has been recently reported to be mediated by glycosaminoglycan regulatory associated long noncoding RNA (GRASLND)." (PMID 40108693, 2025). "MITF expression levels are often used for the phenotypic characterization of melanomas." (PMID 41465443, 2025). "In this study, we used positional synteny to annotate lncRNA components of the MITF network in human melanoma which may also have conserved functions in vertebrate development." (PMID 41336739, 2025). "MiTF's role is context‐dependent, influencing melanoma progression and survival." (PMID 40509563, 2025). "Intriguingly, TTD melanoma cells exhibited reduced proliferation and an increased signature of the melanocyte lineage factor MITF, along with a strong basal upregulation of REDD2, an inhibitor of the mTOR/S6K/4EBP1-dependent messenger RNA (mRNA) translation machinery." (PMID 40918647, 2025). "PACAP treatment increased the nuclear translocation of MITF in both melanoma cell lines." (PMID 41465475, 2025). "Glucose metabolism is regulated by oncogenic BRAF through hypoxia inducible factor 1 alpha (HIF-1 alpha), avian myelocytomatosis viral oncogene homolog (c-Myc), and microphthalmia-associated transcription factor (MITF), and BRAF-mutated melanomas exhibit increased glycolysis." (PMID 40211360, 2025).
melanoma (continued). "However, here we provide evidence that in melanoma cells the methylation of BRD4 is required for the recruitment of MITF." (PMID 40809945, 2025). "Additionally, the impact of oxyresveratrol on melanogenesis and the MC1R/cAMP/MITF signaling pathway was evaluated in B16F10 melanoma cells." (PMID 40594379, 2025). "Furthermore, utilizing an in vivo melanoma metastasis model, they demonstrated that AR increases melanoma lung metastasis by modifying MITF." (PMID 40940929, 2025). "In addition, we show that SETD6 interacts with MITF, a master transcription factor in melanocytes and melanoma, and influences the genomic distribution of MITF." (PMID 40809945, 2025). "Specifically, treatment with PMMEXOs in B16-F10 melanoma cells led to decreased expression of MITF, TYR, TRP-1 and TRP-2, suggesting that PMMEXOs suppress melanin synthesis through the suppression of MITF-mediated transcriptional activation of melanin biosynthetic enzymes." (PMID 40747328, 2025). "Therefore, albeit rare, MITF amplifications can occur in paediatric melanoma and should be included in the genetic analysis of the tumour during diagnosis." (PMID 41168392, 2025). "The use of key immunohistochemical markers, such as S100, SOX10, Melan-A (MART1), HMB-45, and MITF, have demonstrated varying degrees of sensitivity and specificity for the diagnosis of melanoma, assessment of prognostic factors, and guiding of therapeutic decisions." (PMID 40507250, 2025). "Similarly, PPARGC1A (PGC1A), a master regulator of mitochondrial biogenesis regulated by MITF in melanoma, also displayed multiple TFE3 fusion binding sites at the promoter and putative upstream and downstream regulatory elements in the tRCC lines." (PMID 40148585, 2025). "In MITF-high early-stage melanoma, MITF promotes proliferation and limits invasiveness by activating the mechanistic target of rapamycin complex 1 (mTORC1), which sequesters transcription factor E3 (TFE3) in the cytoplasm and directs it for lysosomal degradation, reducing its pro-invasive effects." (PMID 41155412, 2025). "This study showed that PE may target CREB1 and thus regulate the MITF/TYR/DCT axis to reduce melanoma cell viability and the production of melanin." (PMID 40369904, 2025). "Furthermore, histone deacetylase (HDAC) inhibitors have gained attention due to their ability to downregulate the microphthalmia-associated transcription factor (MITF), which plays a crucial role in melanoma progression and therapeutic resistance." (PMID 40508177, 2025). "Specifically, IDO1 inhibition by epacadostat leads to an adverse protection of melanoma cells against IFN-γ-activated T cells, caused by Trp replenishment in the TME that prevents the downregulation of the transcription factor MITF responsible for melanoma cell survival." (PMID 41262240, 2025). "Indeed, in MITF-hypermethylated melanoma cell lines, a demethylation treatment induces a reactivation of the MITF pathway." (PMID 40573249, 2025). "Similarly, co-treatment with α-MSH and fisetin also led to a noticeable reduction in MITF and tyrosinase expression in melanoma cells." (PMID 41373883, 2025). "AR also increased melanoma invasion through regulating the miRNA-539-3p/USP13/MITF/AXL signals." (PMID 41228208, 2025). "However, in contrast to the melanoma rheostat model, from the transitory state, we observed two distinct branches of melanoma transition, with one branch showing complete reduction in MITF and the other an intermediate reduction." (PMID 38183207, 2025). "We previously observed that Rac1-Src signaling appears to drive BRAFi/MEKi resistance selectively in less differentiated melanoma cell lines such as A375 and 451Lu, which display downregulated MITF target gene expression and upregulated YAP/TAZ target gene expression." (PMID 41109929, 2025).
melanoma (continued). "Previously, MITF acetylation by p300 was shown to direct MITF to distinct genomic locations, thereby coordinating the expression of genes that regulate melanocyte and melanoma proliferation and differentiation." (PMID 40809945, 2025). "However, in murine BRAF-transformed melanocytes, overexpression of MITF inhibits proliferation, indicating that the regulation of MITF expression levels by the MAPK pathway plays an important role in the growth of BRAF-driven melanoma." (PMID 40063190, 2025). "MITF can be involved in adaptive redox homeostasis in melanoma cells." (PMID 39970778, 2025). "Additionally, PTX promoted tumor cell differentiation, as evidenced by increased MITF expression and enhanced melanin production, suggesting a potential shift towards a less aggressive melanoma phenotype." (PMID 40806647, 2025). "Certain melanoma subclasses may rely more heavily on MITF for their growth and survival, while others may downregulate MITF as they progress." (PMID 41465475, 2025). "Phosphorylated JNK may play a crucial role in inhibiting melanin production in melanoma cells, likely through negative regulation of the MITF signaling cascade." (PMID 41373883, 2025). "Microphthalmia-associated transcription factor (MITF) is repressed by HDAC inhibitor drugs in multiple cell types and its expression is elevated in melanoma skin samples, wherein its activity may play a role in pathogenesis and treatment resistance." (PMID 40141086, 2025). "MiTF is recognized as a sensitive and relatively specific marker for melanocytes and melanoma." (PMID 40509563, 2025). "It is also the first to identify TYR and MITF as key protein targets of salidroside in melanoma." (PMID 40708947, 2025). "Importantly, the activator of tyrosinase expression, the microphthalmia-associated transcription factor (MITF), plays oncogenic roles in melanoma." (PMID 41002986, 2025). "Moreover, the enhanced phosphorylation of ERK was accompanied by a marked induction of MITF degradation in both human melanoma and α-MSH-induced melanoma cells." (PMID 41373883, 2025). "Future work will reveal whether SETD6 and the methylation of BRD4 are also required for BRD4 and MITF transcriptional activity in regulating specific gene expression programs in melanoma." (PMID 40809945, 2025). "MITF upregulation is frequent in melanoma, especially in the metastatic phase." (PMID 41463281, 2025). "Endogenous PMEL expression is regulated by MITF, with alterations observed in melanoma cells." (PMID 39804725, 2025). "However, the presence of cytotoxic lymphocytes within melanoma tumors likely plays a crucial role in regulating MITF expression." (PMID 39976551, 2025). "In the present study, we revealed that the multi-target mechanism of fisetin inhibits melanogenesis in human melanoma cells by promoting the degradation of β-catenin via activation of PKCα, leading to a reduction in MITF expression and stability through activation of the ERK signaling pathway." (PMID 41373883, 2025). "REDD2 levels were partially driven by MITF and contributed to reduced melanoma proliferation." (PMID 40918647, 2025). "However, MITF’s function in melanoma varies across specimens, where in advanced melanoma MITF is typically downregulated, but has been amplified in select cases." (PMID 40981345, 2025). "Notably, in a subgroup of melanomas with relatively high MITF expression, PGC1 expression is consistently upregulated and correlated with increased mitochondrial biogenesis and oxidative phosphorylation." (PMID 40872623, 2025). "Furthermore, in a study of melanoma cells exposed to UV light, SMARCA4 and MITF inhibited apoptosis and enhanced the trans-responsive effects of the melanoma apoptosis inhibitor ML-IAP." (PMID 39697230, 2024). "Moreover, MITF was found to decrease levels of 8-oxo-G levels, a marker of DNA oxidation, oxidation in vivo when overexpressed in zebrafish melanoma tumors." (PMID 39277608, 2024).